INS (insulin)
Diseases named in the same sentence as INS in open-access papers (continued):
Sharing a sentence is not in itself a finding about the gene and the disease.
breast cancer (continued). "This was different from the disproportionately higher risk associated with insulin use for a longer duration of ≥3 years or ≥5 years for breast cancer mortality." (PMID 26171401, 2015). "This strengthens our idea that if any, the increased risk of breast cancer due to currently used insulin (analogues) is likely to be very small." (PMID 26242987, 2015). "By binding to its receptor, insulin has been shown to have mitogenic and anti-apoptotic effects in several cancers, including breast cancer, and circulating insulin is associated with increased cancer risk and prognosis." (PMID 26111812, 2015). "While these compounds are tested for undesired mitogenic effects, an epidemiological discussion is ongoing regarding an association between insulin analogue therapy and increased cancer incidence, including breast cancer." (PMID 25848982, 2015). "Model II suggested that human insulin users who also had been treated with metformin for ≥2 years had a significantly lower risk of breast cancer (hazard ratio: 0.798, 95 % confidence interval: 0.741-0.859)." (PMID 26537234, 2015). "The aim of this study was to review the postulated association between insulin and insulin analogue treatment and breast cancer development, and plausible mechanisms." (PMID 26242987, 2015). "The epidemiological studies reviewed varied in study design and exposure definition to too large an extent among different insulin analogues to evaluate their impact on breast cancer risk estimates." (PMID 26242987, 2015). "This study discloses a significantly higher risk of breast cancer associated with prolonged use of human insulin." (PMID 26537234, 2015). "High insulin levels are associated with increased breast cancer risk and poor patient survival outcome; therefore, metformin directly and indirectly reduces cancer cell proliferation through reduction of insulin levels and blood glucose levels." (PMID 25866793, 2015). "Elevated insulin levels have been shown to have mitogenic effects and constitute an increased risk factor for breast cancer." (PMID 25866793, 2015). "Patients who used insulin for ≥5 years also consistently had a higher risk of breast cancer mortality compared with the comparison groups, but with a borderline statistical significance (0.05 < P < 0.1)." (PMID 26171401, 2015). "Only three epidemiological studies explored the effect of human insulin as the exposure of interest on the risk of breast cancer." (PMID 26242987, 2015). "For example, elevated levels of insulin are associated with worse prognosis in breast cancer patients, and increased insulin-like growth factor-1 (IGF-1) levels are associated with an elevated risk of prostate and breast cancer." (PMID 24728273, 2014). "Regarding insulin, a positive association with breast cancer risk has been shown for postmenopausal women." (PMID 24969543, 2014). "All but 2 studies identified important confounders or prognostic factors and were used for adjustment of the association between insulin/c-peptide levels and breast cancer." (PMID 24911052, 2014). "In our meta-analysis studies investigating the associations between insulin/C-peptide levels and breast cancer were heterogenous as was the case with the meta-analysis of prospective studies only." (PMID 24911052, 2014). "One recent study confirmed an increased risk of breast cancer for patients given glargine, compared with those given natural insulin." (PMID 23983688, 2013). "High fasting insulin levels are associated with higher risk of colorectal adenoma recurrence and with a poor breast cancer prognosis." (PMID 23983688, 2013). "The roles of progestins, prolactin and insulin are less established but one study showed that risk of ductal breast cancer increases ∼4 fold after use of progesterone." (PMID 24170988, 2013).
breast cancer (continued). "For example, in Sweden during 2006 and 2007, women using insulin glargine alone had an increased incidence risk of breast cancer as compared with women using types of insulin other than insulin glargine." (PMID 23837500, 2013). "The insulin-leptin-adiponectin axis has been implicated mechanistically in breast cancer tumorigenesis." (PMID 22295251, 2012). "Insulin use appeared to be linked to increased cancer risk for all cancer sites studied (except for female breast cancer)." (PMID 22460763, 2012). "Another study demonstrated that a high homeostatic model assessment score, which is associated with serum levels of insulin and glucose, was correlated with increased breast cancer mortality in a sample of 527 women." (PMID 22295251, 2012). "As with breast cancer, the underlying factors appear to be elevated glucose, insulin and IGF-1 levels." (PMID 21773024, 2011). "One of the mechanisms by which insulin has been proposed to increase breast cancer risk is via IGF-I." (PMID 20148110, 2010). "Fasting serum insulin concentration has been directly associated with an increase in both distant recurrence and death in women previously treated for breast cancer." (PMID 21108799, 2010). "Higher weight and stores of body fat are linked to poorer survival and prognosis among patients with breast cancer, most likely mediated by the associated higher levels of oestrogen, insulin and bioavailable insulin-like growth factor-1 (IGF-1)." (PMID 15726121, 2005). "Further experiments implicated decreased serum insulin and insulin-like growth factor I levels in the inhibition of mammary tumor promotion in calorie restricted rats." (PMID 16168107, 2005). "Using data from the National Health and Nutrition Examination Survey (NHANES), we examine the associations of PA with adiposity measures and glucose and insulin metabolism parameters among women and cancer survivors, focusing particularly on breast cancer survivors." (PMID 40937951, 2025). "An antidiabetic diet, which typically focuses on reducing sugar and refined carbohydrates, may help to reduce insulin levels and improve insulin sensitivity, thus lowering the risk of breast cancer." (PMID 39235717, 2025). "This review explores the limited but evolving evidence on menopause in women with T1DM, including age of onset, changes in glycaemic control and insulin requirements, and the effects on bone, metabolic, and cardiovascular health, as well as breast cancer risk and psychological well-being." (PMID 41334715, 2025). "It is hypothesized that metformin may reduce breast cancer risk by lowering insulin levels or activating AMPK to inhibit cancer cell growth." (PMID 39857949, 2025). "Due to the potential for high insulin levels caused by insulinoma to promote rapid progression of breast cancer, and the patient's recurrent hypoglycemic symptoms, a multidisciplinary team (MDT) discussion at our hospital suggested addressing the insulinoma with minimal invasiveness as a priority." (PMID 40550558, 2025). "Numerous studies have demonstrated an inverse relationship between physical activity and breast cancer risk, with proposed mechanisms including reductions in systemic inflammation, improved immune function, hormonal regulation, and enhanced insulin sensitivity." (PMID 40283700, 2025). "Physical inactivity has been related to an increased risk of a variety of health problems, including breast cancer, through various mechanisms such as hormonal changes, body weight and fat distribution, insulin sensitivity, inflammation, immunological function, and biomarker changes." (PMID 39610935, 2024). "Insulin may directly impact breast cancer risk by mitogenic properties, increasing IGF-I secretion and decreasing IGF-I binding proteins, inhibiting sex hormone-binding protein (SHBG) synthesis, and raising bioavailable estrogen levels." (PMID 38999846, 2024).
breast cancer (continued). "The objectives of the current study were 1) to analyze the association between BMI and MBD with breast cancer molecular subtypes and 2) to study the possible differences between cholesterol, vitamin D, and insulin levels in recently diagnosed early breast cancer." (PMID 38734800, 2024). "Increased insulin levels are associated with higher breast cancer incidence and mortality." (PMID 39251829, 2024). "Additionally, insulin therapy is often linked to an increased incidence of a variety of cancers, including sex-specific tumors such as breast cancer." (PMID 37375800, 2023). "However, further studies with larger sample sizes are needed to investigate these associations and explore the potential biological mechanisms linking insulin and other biological markers with breast cancer risk." (PMID 37096432, 2023). "Inflammatory, insulin and oestrogenic pathways have been linked to breast cancer (BC)." (PMID 36737658, 2023). "Elevated circulating levels of insulin could also influence breast cancer risk by regulating sex hormone synthesis and chronic inflammation which in turn increase the risk of the disease." (PMID 37096432, 2023). "Given that C‐peptide levels seemed to be higher among MUOW/OB women (5.23 ng/mL) compared to MUNW women (4.75 ng/mL), it could also be possible that a much higher insulin level is required to increase breast cancer risk." (PMID 37096432, 2023). "A possible mechanism underlying the elevated risk of postmenopausal breast cancer among MUOW/OB women may implicate a direct effect of insulin which acts as a cancer promoter through its known mitotic and anti‐apoptotic activities." (PMID 37096432, 2023). "In addition, metformin, a widely used treatment for patients with T2D, has been associated with lower breast cancer-specific mortality through mechanisms that induce a reduction in glucose and insulin levels." (PMID 36737658, 2023). "Postmenopausal women with an increased risk of breast cancer show improved hormonal (bioavailable estradiol, testosterone, and insulin) and adipocytokine (relative adiponectin/leptin, C-reactive protein) markers of breast cancer in serum and breast tissue with weight loss of more than 10%." (PMID 35752704, 2022). "For postmenopausal breast cancer risk, a decrease in adiposity, thus a decrease in estrogen and insulin signaling, could be responsible for physical activity-mediated risk reduction." (PMID 35454864, 2022). "Several serum molecules associated with obesity provide a molecular link to breast cancer, including increased circulating levels of insulin, glucose, hormones, adipokines, and inflammatory mediators that could affect breast tissue." (PMID 35413055, 2022). "Additionally, it has been shown that high levels of insulin caused by abnormal insulin secretion kinetics are positively correlated with breast cancer progression." (PMID 35045088, 2022). "Analysis of bulk RNA-Seq revealed a decrease in WSCD2 gene expression in the samples from TCGA breast cancer patients with the genotype homozygous for the minor alleles and core gene networks of transcription factors, growth factors and insulin indirectly associated with MT-ND4." (PMID 35082309, 2022). "Insulin and associated metabolic pathways are associated with breast cancer recurrence and hypothesized to be a mechanistic driver of cancer." (PMID 34578984, 2021). "The highest levels of fasting insulin were significantly associated with distant recurrence and death, even after adjustment for body mass index (BMI), age, hormonal receptor status, and other known prognostic factors in breast cancer." (PMID 34830886, 2021). "It has been suggested that physical activity may mediate breast cancer risk by decreasing insulin levels and influencing insulin-like growth factors and binding proteins." (PMID 34771713, 2021). "Exercise and weight loss are associated with decreased breast cancer recurrence, which may be mediated through reduced insulin levels and improved insulin sensitivity." (PMID 34578984, 2021).
breast cancer (continued). "In addition, some studies have pointed out that high insulin levels are associated with increased breast cancer risk and poor prognosis." (PMID 33976288, 2021). "Two large studies indicated that serum insulin is positively associated with breast cancer risk." (PMID 32631390, 2020). "In one previous study users of insulin glargine and users of other insulin analogs had a lower risk of cancer in general than those using human insulin, but on the other hand, an increased risk of breast cancer in users of insulin glargine in comparison with users of human insulin was found." (PMID 33585194, 2020). "In order to identify that whether EMT induced by insulin in breast cancer cells is mediated by NR2F2, we performed loss of function experiments in our in vitro model." (PMID 32631390, 2020). "Similar to IGF-1, insulin is also a mitogen and plays a significant role in breast cancer, and this might be related to underlying insulin resistance." (PMID 32528752, 2020). "Among insulin users, an increased risk of breast cancer was reported." (PMID 33585194, 2020). "Additionally, insulin exhibits potent anabolic properties and has been implicated in many malignancies, including breast cancer." (PMID 31936350, 2020). "Some epidemiologic studies indicated that fasting insulin levels might represent a risk factor for some cancer types such as colorectal, endometrium, and breast cancer." (PMID 32907593, 2020). "In our study also, insulin use was associated with an increased incidence of breast cancer." (PMID 30895533, 2019). "Besides breast cancer risk, insulin and IGF-1 levels have been positively connected to recurrence and mortality." (PMID 30634494, 2019). "Furthermore, it has been suggested that the use of glargine (a long-acting insulin analogue that is used in patients with diabetes) is associated with an increased incidence of breast cancer." (PMID 30895533, 2019). "However, use of insulin at any time was observed to be weakly associated with an increased incidence of breast cancer (HR 1.18, 95% CI 1.03–1.35)." (PMID 30895533, 2019). "Remarkably, weight loss interventions through diet and exercise in overweight/obese breast cancer survivors were associated with a decrease in specific biologic factors related to breast cancer recurrence and mortality, such as estrogen, insulin, and leptin levels." (PMID 30634494, 2019). "Furthermore, increasing cumulative use of insulin was observed to be positively associated with the risk of breast cancer in a monotonic manner." (PMID 30895533, 2019). "In this prospective case-control study nested within the Mano a Mano Cohort Study, we assessed the risk of breast cancer with regard to plasma levels of c-peptide, gastric inhibitory polypeptide, insulin, leptin, monocyte chemoattractant protein-1, pancreatic polypeptide, and peptide YY." (PMID 31292496, 2019). "However, insulin use was found to be associated with a slightly increased incidence of breast cancer in the full cohort as well as in the case–control analysis." (PMID 30895533, 2019). "Medication that increases insulin levels may be associated with higher cancer risks; by contrast, treatment with insulin sensitizers, including metformin, may reduce breast cancer risk." (PMID 31717292, 2019). "However, insulin use (especially cumulative use) was found to be associated with an increased incidence of breast cancer." (PMID 30895533, 2019). "Furthermore, in patients with breast cancer (BC), higher circulating insulin levels have been found to be associated with an adverse outcome." (PMID 31535085, 2019). "However, the increased risk of breast cancer has mainly been associated with long-term use of the insulin analogue glargine." (PMID 30895533, 2019).
breast cancer (continued). "The aims of this study were to investigate the association of insulin therapy with mammographic density (MD) as an intermediate phenotype for breast cancer and to assess associations with long-term elevated circulating insulin levels using a genetic score comprising 18 insulin-associated variants." (PMID 30092829, 2018). "Specifically, large-scale epidemiological studies published in 2009 raised the concern that insulin analogs, especially glargine, might increase breast cancer risk." (PMID 29615978, 2018). "The increase in serum insulin/insulin resistance and insulin-like growth factor associated with these disorders is one likely mechanism, as they are associated with an increase in breast cancer incidence and a worse prognosis." (PMID 29780974, 2018). "Thus, the abnormality in insulin signaling is one of the common associations between Type II diabetes and breast cancer." (PMID 30515357, 2018). "Likewise the current study identifies favorable shifts in insulin parameters among breast cancer survivors who achieve weight loss." (PMID 29587682, 2018). "Significant improvements in serum insulin in breast cancer survivors achieving ≥ 5% weight loss have been identified previously where participants reaching this degree of weight loss experienced 21.9% decrease in serum insulin with weight loss and exercise." (PMID 29587682, 2018). "An alternative explanation for the inverse relationship between adolescent body size and breast cancer risk might be due to increased serum insulin and androgen levels, which can lead to anovulatory menstrual cycles and reduced exposure to sex hormones." (PMID 28732505, 2017). "Although circulating levels of insulin, IGF-1, GH and LEP in relation to breast cancer have been well studied, less is known about how germline variation in the insulin, IGF, GH, and LEP signaling pathways may affect risk of breast cancer." (PMID 27942580, 2016). "High levels of IGF1 and insulin in humans have been linked to increased risk of breast cancer." (PMID 27255182, 2016). "Beyond breast cancer risk, insulin and IGF-1 stimulate cancer progression and invasion." (PMID 27338371, 2016). "There were significant post-intervention changes for weight (>10% loss), fruit and vegetable consumption (+3.7 ± 4.3 servings/day), and physical activity (+1235 ± 832 kcal/week), and reductions in two biochemical mediators of breast cancer risk, fasting insulin (−16.7%) and leptin (−37.1%)." (PMID 27376159, 2016). "According to our results, showing an increased prevalence of insulin use among cases than among controls, insulin treatment may increase the risk of breast cancer." (PMID 25916213, 2016). "Additional analyses suggested that the risk of breast cancer associated with human insulin use might be modified by a combination use of other medications including metformin, statin and ACEI/ARB (Models II to IV)." (PMID 26537234, 2015). "Furthermore, the temporal relationship between the cause (insulin exposure) and effect (breast cancer mortality) is true." (PMID 26171401, 2015). "However, there are very limited human/epidemiological data from only two studies on the association of tumour subtypes and insulin (analogues) exposure among diabetic patients with breast cancer." (PMID 26242987, 2015). "The increased risk of breast cancer associated with human insulin use may be modified by medications such as metformin, statin and ACEI/ARB." (PMID 26537234, 2015). "For example, in a sample of women enrolled in the Women’s Health Initiative Observational Study, investigators found that women in the highest tertile of baseline insulin had nearly double the risk of breast cancer relative to women in the lowest tertile (HR: 2.22; 95% CI 1.39–3.53)." (PMID 26305095, 2015). "Insulin may also enhance breast cancer risk, especially in postmenopausal women, by increasing levels of estrogens and androgens." (PMID 26030767, 2015).